CXCR4 (C-X-C motif chemokine receptor 4)
Diseases named in the same sentence as CXCR4 in open-access papers (continued):
Sharing a sentence is not in itself a finding about the gene and the disease.
Insulin resistance (5 papers, 2019 to 2022). Increased resistance towards insulin, that is, diminished effectiveness of insulin in reducing blood glucose levels. "Hence, these results suggest that glucose metabolism in CXCR4-deficient mice was deteriorated owing to insulin resistance." (PMID 30992469, 2019). "According to our GSEA results, CXCR4 coexpression genes are enriched during metabolism biological processes of adipogenesis and insulin resistance." (PMID 35774848, 2022). "Our combined GSEA results indicate that cholesterol metabolism and insulin resistance may regulate complex signaling pathways and antitumor immunity and play important roles in high CXCR4 expression DLBCL." (PMID 35774848, 2022). "The mechanism of insulin resistance in CXCR4-deficient mice was not precise in the present study." (PMID 30992469, 2019). "We hypothesize that CXCR4 antagonists may simultaneously inhibit MAPK, PI3k/AKT, and mTOR signaling pathway, inhibit cholesterol metabolism, and correct insulin resistance, which may exert a stronger inhibitory effect on the BCR signaling pathway." (PMID 35774848, 2022). "Body weight gain and glucose metabolism failure without CXCR4 in the BAT were observed along with insulin resistance after feeding mice with HFD." (PMID 30992469, 2019).
pituitary tumor (5 papers, 2014 to 2020). A benign or malignant neoplasm affecting the pituitary gland. "CXCL12 mRNA is expressed in about 2/3 of GH-secreting pituitary tumors and NF-PitNETs, with CXCR4 mRNA expressed in almost all these tumors." (PMID 33362712, 2020). "Further study proved that CXCL12/CXCR4 mediate the DNA synthesis and cell proliferation by human pituitary tumor primary cultures." (PMID 33362712, 2020). "CXCR4 expression has been reported in the rat pituitary and in human pituitary tumor cells, but within the human pituitary specimens of normal appearance analyzed in this work, only a minority of cells displayed detectable CXCR4 antibody reactivity." (PMID 29554149, 2018). "In pituitary tumor cells, CXCR4 inhibition by a peptide antagonist induced apoptosis through activation of the caspase-3 pathway." (PMID 26954567, 2016).
Splenomegaly (5 papers, 2012 to 2025). Abnormal increased size of the spleen. "Recently, JAK2 activation in MPL-mutant cells was found to support the CXCL12/CXCR4 pathway and activate downstream JAK-STAT, PI3K/AKT, and RAS/MAPK activation pathways, leading to the expansion of malignant clones, EMH, and splenomegaly in MF patients." (PMID 29562644, 2018). "Therefore, each mechanism, namely the CXCL12/CXCR4 pathway and low Gata1 expression, individually leads to the progression from EMH to splenomegaly in MF patients." (PMID 29562644, 2018). "Because SDF-1/CXCR4 axis modulates homing, BM retention and mobilization of HSCs, a marked decrease of SDF-1 in the high SFFV-FGF2 group may have led to substantial stem cell mobilization, contributing to splenomegaly." (PMID 22629419, 2012).
Vestibular schwannoma (5 papers, 2018 to 2023). A vestibular schwannoma (also known as acoustic neuroma, acoustic neurinoma, or acoustic neurilemoma) is a benign, usually slow-growing tumor that develops from the VIIIth cranial nerve supplying the inner ear. "In the previous reports, it had been demonstrated that CXCR4 was upregulated in sporadic Vestibular schwannomas (VS) as well as in neurofibromatosis type 2 (NF2) tumors." (PMID 34266404, 2021). "We conclude that CXCR4 represents a potential target for a systemic therapeutic approach, especially in NF2-associated vestibular schwannomas." (PMID 29515781, 2018). "Western blotting analysis of proteins from vestibular schwannomas revealed four CXCR4 isoforms of approximately 190 kDa, 72 kDa, 55 kDa, and 42 kDa." (PMID 29515781, 2018). "CXCR4 protein expression was also detected by immunohistochemical analysis of sections of vestibular schwannomas." (PMID 29515781, 2018). "Double immunofluorescence staining of vestibular schwannomas for CXCR4 and the Schwann cell protein S100 revealed co-localization of these proteins." (PMID 29515781, 2018). "We have recently demonstrated CXCR4 overexpression in vestibular schwannomas (VS)." (PMID 31245296, 2019). "Therefore, we examined the expression and spatial distribution of CXCR4 in sporadic and NF2-associated tumor tissue and evaluated its potential role as a prognostic marker for vestibular schwannoma." (PMID 29515781, 2018). "We hypothesized that CXCR4 might be an interesting therapeutic target for the treatment of vestibular schwannoma." (PMID 29515781, 2018). "CXCR4 expression was not significantly different in NF2-associated vestibular schwannomas than in sporadic vestibular schwannoma." (PMID 29515781, 2018). "Vestibular schwannomas showed 4.6-fold higher CXCR4 mRNA expression than control samples." (PMID 29515781, 2018). "Thus, CXCR4 was expressed in the Schwann cells of vestibular schwannomas." (PMID 29515781, 2018). "We examined CXCR4 expression in vestibular schwannomas (VS) from patients with and without neurofibromatosis type 2 (NF2) and correlated the levels with the patients’ clinical characteristics." (PMID 29515781, 2018). "The present investigation demonstrates for the first time in a larger cohort that CXCR4 is overexpressed in pure vestibular schwannomas with and without NF2 and could therefore play a role in the pathogenesis of these tumors." (PMID 29515781, 2018). "However, there are no data on CXCR4 expression in vestibular schwannomas in patients with or without NF2, nor has CXCR4 expression been correlated with other clinical data." (PMID 29515781, 2018).
AIDS dementia (4 papers, 2012 to 2024). "Moreover, CXCR4 is upregulated in microglia and astrocytes in various brain diseases, such as HIV encephalitis and experimental allergic encephalomyelitis." (PMID 29719536, 2018). "In addition to being the only subject with CXCR4-using virus in the CSF, subject 17 was also the only subject diagnosed with severe symptoms (HIV encephalopathy) and one of three subjects with a CSF HIV RNA load higher than in plasma (difference 1.21 log10 copies/mL)." (PMID 38713307, 2024).
allergic disease (4 papers, 2017 to 2025). An immune response that occurs following re-exposure to an innocuous antigen, and that requires the presence of existing antibodies against that antigen. "Our study newly identified six loci associated with allergic diseases (MIIP, CXCR4, SCML4, CYP1B1, ICOS and LINC00824) and four pleiotropic loci associated with both autoimmune and allergic diseases (PRDM2, G3BP1, HBS1L and POU2AF1)." (PMID 35753705, 2022). "CXCR4 is primarily expressed by naïve and TH2 cells, eosinophils and mast cells, where it plays a significant role in TH2-type allergic diseases." (PMID 28199695, 2017).
anaplastic thyroid cancer (4 papers, 2014 to 2022). "The expression of the five SSTs and of CXCR4 was assessed in 90 samples from 56 patients with follicular, papillary, medullary, or anaplastic thyroid carcinoma by means of immunohistochemistry using well-characterised monoclonal antibodies." (PMID 35799158, 2022). "In another study, CXCR4 RNAi blocked SDF-1-induced proliferation of anaplastic thyroid carcinoma cells and increase in phosphorylation of extracellular signal-regulated kinases." (PMID 24647809, 2014). "Treatment of anaplastic thyroid carcinoma cells with SDF-1 induces proliferation, which is blocked by the specific CXCR4 antagonist AMD3100 and by CXCR4 RNA interference, and AMD3100 effectively reduces tumor growth in nude mice inoculated with different anaplastic thyroid carcinoma cells." (PMID 24647809, 2014).
Anxiety (4 papers, 2017 to 2025). Intense feelings of nervousness, tension, or panic often arise in response to interpersonal stresses. "These behavioral results demonstrate that the Cxcl12/Cxcr4 chemokine system has a role in mediating these ethanol-induced changes in locomotor and anxiety-like behaviors." (PMID 36702854, 2023). "For example, pharmacological blockade of CXCR4 attenuates the conditioned rewarding and locomotor stimulant effects of MDPV, while blockade of CXCR4, CCR5, or IL-17A signaling attenuates changes in anxiety-like behaviors evoked by MDPV." (PMID 38025384, 2023).
B-cell neoplasm (4 papers, 2020 to 2025). A group of heterogeneous lymphoid tumors generally expressing one or more B-cell antigens or representing malignant transformations of B-lymphocytes. "Another reported CXCR4 mutation in WM and other B cell neoplasms was c.1012C>T (COSV54010080), although there is limited data on its predictive impact on progression." (PMID 40666506, 2025). "CD19-targeted immunotherapies such as mAbs and CAR-T cells have already demonstrated clinical success across multiple B-cell neoplasms; however, resistance mechanisms driven by CXCR4-mediated microenvironmental protection may similarly undermine these therapeutic approaches." (PMID 40076664, 2025).
basal cell carcinoma (4 papers, 2012 to 2021). A carcinoma involving the basal cells. "Transforming growth factor-β1 (TGF-β1) might upregulate the CXCR4 expression in basal cell carcinoma (BCC) cells." (PMID 34630738, 2021). "Their expression of CXCR4 forms part of the CXCR4/SDF-1 axis, which is crucial in skin regulating cutaneous wound healing, systematic lupus erythematosus and angiogenesis of basal cell carcinoma." (PMID 31440236, 2019).
colon adenocarcinoma (4 papers, 2018 to 2024). "Known Hsp90 clients EGFR, HER2, CDK4, CDK6, CXCR4, Akt-1, c-Raf, Survivin, ERK-5 and Integrin α2 were analyzed following the administration of KUNB31 to HT29 (colon adenocarcinoma grade II) cells." (PMID 29382832, 2018).
diabetic kidney disease (4 papers, 2014 to 2024). Progressive kidney disorder caused by vascular damage to the glomerular capillaries, in patients with diabetes mellitus. "When SDF-1-CXCR4-related maladaptive control occurred, podocyte progenitors of the Bowman’s capsule would proliferate in crescentic glomerulonephritis, hypoxia-induced upregulation of CXCR4 in nephrosclerosis was observed, and there was insufficient podocyte regeneration in diabetic nephropathy." (PMID 25029540, 2014). "Both CXCR4 (red) and β-catenin (green) were induced and colocalized in the glomeruli of mice in hypertensive nephropathy induced by chronic infusion of angiotensin II (Ang II), diabetic nephropathy in genetic db/db mice, and remnant kidney model induced by 5/6NX." (PMID 34976212, 2022).
diabetic retinopathy (4 papers, 2013 to 2023). "Odds ratios (ORs) and 95% confidence intervals (CIs) of diabetic retinopathy associated with SDF-1α/CXCR4 axis genotypic frequencies in age ≤60." (PMID 38075689, 2023). "Odds ratios (ORs) and 95% confidence intervals (CIs) of diabetic retinopathy associated with SDF-1α/CXCR4 axis genotypic frequencies." (PMID 38075689, 2023). "This study investigated whether single-nucleotide polymorphisms (SNPs) of SDF-1 and its receptor CXCR4 are correlated with diabetic retinopathy (DR)." (PMID 38075689, 2023). "Stromal cell-derived factor-1 (SDF-1) and its receptor CXC chemokine 4 (CXCR4) have been demonstrated to play critical roles in diabetic retinopathy (DR)." (PMID 38075689, 2023). "In conclusion, our study raised the hypothesis that DPP4-inhibitors might aggravate diabetic retinopathy by increasing vascular permeability through the SDF-1α/CXCR4 axis, followed by Src activation and phosphorylation of VE-cadherin." (PMID 27381080, 2016). "We tested the hypothesis of whether DPP4-inhibitors, by stimulating the SDF-1α/CXCR4 axis and subsequently resulting in Src-mediated phosphorylation of VE-cadherin, would increase vascular permeability, which is a key process in diabetic retinopathy." (PMID 27381080, 2016). "However, DPP4-inhibitors might have adverse effects on diabetic retinopathy by promoting vascular leakage because DPP4-inhibitors increase active SDF-1α concentration which would activate the SDF-1α/CXCR4/Src pathway." (PMID 27381080, 2016). "Furthermore, this may indicate that fvERM cells are not the migrating cells in diabetic retinopathy in response to increased local SDF1α, nor that cell migration occurs via the well-known SDF1α-CXCR4 axis." (PMID 24195074, 2013).
endometrial adenocarcinoma (4 papers, 2011 to 2021). "CD133-positive cells purified from endometrial adenocarcinomas displayed a higher level of proteins associated with tumor progression (e.g., matrix metalloproteases, interleukin-8, CD44, and CXCR4)." (PMID 34063525, 2021). "A previous study conducted in Ishikawa endometrial adenocarcinoma cells have suggested that E2 could induce CXCR4 expression at the transcriptional level." (PMID 21695171, 2011).
gallbladder cancer (4 papers, 2015 to 2024). "Yao et al13 conducted a study, in which the expressions of CXCR4 and CXCR7 in gallbladder cancer specimens from 72 patients were analysed, and found that cytoplasmic CXCR4 expression (P = .006) and CXCR7 expression (P = .035) were independent prognostic factors for survival." (PMID 32512633, 2020).
gastric adenocarcinoma (4 papers, 2013 to 2021). "Specifically, our case would suggest an involvement of the CXCL12 (SDF-1)/CXCR4 axis in the observed metastasis of DLBCL to primary gastric adenocarcinoma." (PMID 34187383, 2021). "CXCR4 expression was retrospectively analyzed by immunohistochemistry in 97 patients with gastric adenocarcinoma from China." (PMID 23936528, 2013).
glomerulosclerosis (4 papers, 2014 to 2023). A hardening of the kidney glomerulus caused by scarring of the blood vessels. "Podocyte-specific deletion of CXCR4 inhibits β-catenin activation, reduces proteinuria, ameliorates podocyte injury and glomerulosclerosis." (PMID 34976212, 2022). "Podocyte-specific knockout of CXCR4 in mice abolished β-catenin activation, preserved podocyte integrity, reduced proteinuria and ameliorated glomerulosclerosis after Adriamycin injury." (PMID 34976212, 2022). "Podocyte-specific deletion of CXCR4 blunts β-catenin activation, ameliorates podocyte injury, reduces proteinuria and glomerulosclerosis, thereby halting the progression of CKD." (PMID 34976212, 2022). "Furthermore, inhibition of CXCR4 alleviates podocyte injury, proteinuria and glomerulosclerosis." (PMID 34976212, 2022). "In particular, the immune–histological analysis evidenced that chemokine C-X-C motif receptor 4 (CXCR4) and 12 (CXCR12) have pivotal roles in induced hypoxia, leading to both tubulointerstitial fibrosis and glomerulosclerosis in NAS." (PMID 36902062, 2023).
hepatoblastoma (4 papers, 2017 to 2025). Hepatoblastoma (HB) is a malignant hepatic tumor and is the most common pediatric liver cancer. "In hepatoblastoma, C-X-C chemokine receptor type 4 (CXCR4) is highly expressed in TINs, while its ligand C-X-C motif chemokine ligand (CXCL) 12 is expressed at much higher levels in the tumor than in the surrounding tissue." (PMID 41326356, 2025). "Our results showed that the candidates CD133, CXCR4, CD34, CD90 and OV-6 binding were detected at different expression levels in the two investigated hepatoblastoma cell lines (HuH6 and HepG2)." (PMID 34685577, 2021). "In order to define a set of markers for the identification of CSCs in hepatoblastoma, we analyzed the expression of CD133, CXCR4, CD34 and CD90 in the hepatoblastoma cell lines HepG2 and HuH6 using flow cytometry." (PMID 34685577, 2021).
Hypercholesterolemia (4 papers, 2012 to 2020). An increased concentration of cholesterol in the blood. "Till present, CXCR4 is the main factor identified to be responsible for HSPC mobilization in hypercholesterolemia." (PMID 25546260, 2015). "In addition, CXCR4 has been identified as a key factor in hypercholesterolemia-induced HSPC mobilization from BM into PB." (PMID 25546260, 2015).
inflammatory skin disease (4 papers, 2021 to 2025). Inflammatory skin disorders covers a broad category that includes many conditions ranging in severity, from mild itching to grave medical health complications These disorders are common in people of all ages and races. "In addition, we identify the CXCR4/CXCL12 axis as a potential therapeutic target in inflammatory skin diseases." (PMID 37736772, 2023). "In summary, these results demonstrate a pivotal role of CXCR4hi neutrophils in promoting skin inflammation and suggest targeting of CXCL12/CXCR4 axis may have a role in treatment of inflammatory skin diseases." (PMID 37736772, 2023).
interstitial lung disease (4 papers, 2018 to 2023). A diverse group of lung diseases that affect the lung parenchyma. "An increased specific CD4+ T cell subtype (CD4+CXCR4+ T cell) was significantly associated with the severity and mortality of idiopathic inflammatory myopathy-associated interstitial lung disease." (PMID 33959573, 2021). "Moreover, the presence of Abs against CXCR3 and CXCR4 in SSc patients indicates a link between autoimmunity and interstitial lung disease, in which both Abs strongly correlate with each other and their concentrations can discriminate patients with stable or decreasing lung function." (PMID 37359516, 2023). "For instance, higher levels of CXCR3 and CXCR4 Abs have been observed in the sera of SSc patients compared to the healthy controls, where higher levels of CXCR3 in patients with interstitial lung disease correlate with worse lung function." (PMID 37359516, 2023).
intrahepatic cholangiocarcinoma (4 papers, 2015 to 2025). A carcinoma that arises from the intrahepatic bile duct epithelium in any site of the intrahepatic biliary tree. "In addition, knockdown of the receptor of CXCL12, namely, CXCR4, downregulated mesenchymal markers including Slug in intrahepatic cholangiocarcinoma." (PMID 34118928, 2021).
invasive ductal carcinoma (4 papers, 2016 to 2021). "Since miR-139 was found to downregulate CXCR4 and thus inhibit tumor cell aggressiveness both in vitro and in vivo, we next measured miR-139 levels in women diagnosed with invasive ductal carcinoma (IDC)." (PMID 34070538, 2021). "CXCR4 and ACKR3 expression was assessed in patient samples with invasive ductal carcinoma (left) and invasive lobular carcinoma (right) using immunohistochemistry." (PMID 30441765, 2018).
ischemic cardiomyopathy (4 papers, 2015 to 2019). Ischemic cardiomyopathy is a cardiomyopathy in which a weakness in the muscle of the heart due to inadequate oxygen delivery to the myocardium with coronary artery disease being the most common cause. "The transient overexpression of SDF-1 in ischemic cardiomyopathy has been shown to lead to long-term down-regulation of cardiac myocyte CXCR4 expression, re-recruiting the contractile function of the border zone." (PMID 26441982, 2015). "The CXCL12 (also known as SDF-1)/CXCR4 axis has been previously reported to be involved in the retention and mobilization of stem cells in the adult ischemic cardiomyopathy, supporting the notion that CXCL12 might have therapeutic potential." (PMID 31029167, 2019). "In addition, the enhancement of CXCR4 expression with HMGB1 treatment promotes the local migration to damaged tissue through the SDF-1/CXCR4 axis, which might be essential in DCM as well as ischemic cardiomyopathy." (PMID 30517097, 2018).
ischemic disease (4 papers, 2017 to 2024). Lack of blood supply to an area of the body, resulting in impairment of tissue oxygenation. "Additionally, miR-126 could enhance EPC homing to thrombogenic and ischemic area by targeting PIK3R2 and CXCR4, which plays an important role in the therapeutic effect of EPCs on ischemic diseases." (PMID 29760722, 2018).